MAGEA4 (MAGE family member A4)
Description:
Regulates cell proliferation through the inhibition of cell cycle arrest at the G1 phase.
Synonyms: CT1.4; MAGE4; MAGE4A; MAGE4B; MAGE-41; MAGE-X2; MGC21336
Tractability: Small molecule: a structure with a bound ligand is known. PROTAC: ubiquitination databases record sites on it.
Gene: Protein-coding gene on chromosome X (151,912,495 to 151,925,173, forward strand). Ensembl gene ENSG00000147381.
Subcellular location (Human Protein Atlas): Nuclear speckles; Cytosol
Gene Ontology:
Molecular function: protein binding; histone deacetylase binding
Biological process: negative regulation of apoptotic process; positive regulation of cell cycle; negative regulation of transcription by RNA polymerase II
Cellular component: nucleus
Homologues: Orthologues: chimpanzee MAGEA4 (97% identical), macaque MAGEA4 (92% identical), mouse Magea13 (38% identical), rat Magea13 (38% identical), zebrafish ndnl2 (20% identical), Drosophila melanogaster MAGE (16% identical). Paralogues in human: MAGEA1 (75% identical), MAGEA8 (72% identical), MAGEA12 (68% identical), MAGEA3 (67% identical), MAGEA6 (67% identical), MAGEA2 (67% identical), MAGEA2B (67% identical), MAGEA9 (64% identical), MAGEA9B (64% identical), MAGEA11 (62% identical), MAGEA10 (54% identical), MAGEB16 (47% identical), and 25 more.
Diseases named in the same sentence as MAGEA4 in open-access papers:
MAGEA4 is named in the same sentence as 98 diseases in open-access papers, as found by Europe PMC text mining. Sharing a sentence is not in itself a finding about the gene and the disease. The quoted sentences say what the papers report.
melanoma (34 papers, 2010 to 2026). A malignant, usually aggressive tumor composed of atypical, neoplastic melanocytes. "MAGEA4 was found to be highly expressed in melanoma, pancreatic cancer, lung cancer, and esophageal squamous cell carcinoma." (PMID 38099574, 2023). "In this study, five different melanoma antigens, MAGEA4, MAGEA10, MART1, TRP1 and MCAM, were incorporated into the VLPs and their localization within the particles was determined." (PMID 27403717, 2016). "Five different melanoma antigens, MAGEA4, MAGEA10, MART1, TRP1 and MCAM, were co-expressed with the MLV Gag protein in mouse fibroblast cells, and their incorporation into VLPs and localization within the particles were determined." (PMID 27403717, 2016). "For example, MAGEA1 is upregulated in lung cancer, melanoma, and gastric cancer; MAGEA3 is upregulated in breast and lung cancer; MAGEA4 is upregulated in melanoma; MAGEA5 is upregulated in head and neck cancer; and MAGEA9 is upregulated in liver and colon cancer." (PMID 34202157, 2021). "A total of 10137 melanoma cells were further grouped into seven subtypes, i.e., C0 Melanoma BIRC7, C1 Melanoma CDH19, C2 Melanoma EDNRB, C3 Melanoma BIRC5, C4 Melanoma CORO1A, C5 Melanoma MAGEA4, and C6 Melanoma GJB2." (PMID 37435067, 2023). "To evaluate the efficacy of MAGEA4-directed TCR-like CAR-T cells in a solid tumor model in vivo, we introduced human melanoma cells SK-Mel-37 expressing MAGEA4 into NRG mice." (PMID 37894816, 2023). "Module M3 contained JUND, SOX2, THAP11, and JUN, as well as regulators for C5 Melanoma MAGEA4, C6 Melanoma GJB2, C2 melanoma EDNRB, and C1 melanoma CDH19." (PMID 37435067, 2023). "A total of 10137 melanoma cells were clustered into 7 subtypes (C0 Melanoma BIRC7, C1 Melanoma CDH19, C2 Melanoma EDNRB, C3 Melanoma BIRC5, C4 Melanoma CORO1A, C5 Melanoma MAGEA4, C6 Melanoma GJB2)." (PMID 37435067, 2023). "All five melanoma antigens, the MART1, TRP1, MCAM, MAGEA4 and MAGEA10 proteins were detected in respective VLP’s confirming once again the effective incorporation of recombinant proteins into VLPs induced by overexpression of the MLV Gag protein." (PMID 27403717, 2016). "We undertook a mutational analysis of coding regions of four CT-X MAGE genes, MAGEA1, MAGEA4, MAGEC1, MAGEC2 and the ubiquitously expressed MAGEE1 in human melanoma samples." (PMID 20862285, 2010). "Furthermore, we found that the highest regulon activity scores of melanoma cell subtypes in M1-M4 were C4 Melanoma CORO1A (M1), C4 Melanoma CORO1A (M2), C5 Melanoma MAGEA4 (M3), and C1 Melanoma CDH19 (M4), respectively." (PMID 37435067, 2023). "However, expression of TDRD9 is not correlated with that of MAGEA1, MAGEA2, MAGEA3, or MAGEA4, which are CTA genes often expressed in lung cancer and melanomas." (PMID 29515758, 2018).
synovial sarcoma (34 papers, 2018 to 2026). "Targeting fusion-derived cancer testis antigens such as NYESO-1 and MAGEA-4 has shown benefits in limited sarcomas such as synovial sarcoma and Myxoid/Round Cell Liposarcoma." (PMID 37007160, 2023).
ovarian carcinoma (28 papers, 2012 to 2025). A malignant neoplasm originating from the surface ovarian epithelium. "In our previous study, some XCTAs, including XAGE3 and MAGEA4, were overexpressed in ovarian cancer with a loss of XCI." (PMID 26360551, 2015). "Interestingly, MAGEA4 has been associated with XCI dysregulation in ovarian cancers." (PMID 37759468, 2023). "Only KTR14, KRT16, CXCL9, and CFD in BRCA1 Ovarian Cancer and TSPAN7 and CDKN2C in BRCA2 ovarian cancers were highly upregulated, and KANK4, MFGE8, LINC00346, and SA100A1 in BRCA1 mutated breast cancer, and MAGEA4 in BRCA2 breast cancers." (PMID 40647506, 2025). "Over-expression of MAGEA4 was previously reported in other malignancies, such as lung cancer and ovarian cancer." (PMID 26909861, 2016). "Previous studies that investigated MAGEA4 in ovarian cancer reported tissue expression in 57% of serous carcinomas and 47% of epithelial ovarian cancer patients, serum levels in 22% of primary ovarian cancer patients and autologous antibodies in 9% of epithelial ovarian cancer patients." (PMID 34681879, 2021). "Previously, high expressions of MAGEA4 and PIWIL1 were found in epithelial ovarian cancer; furthermore, the expression of PRAME was found in ovarian, uterine, and other tumor types." (PMID 37835834, 2023).
lung carcinoma (23 papers, 2012 to 2025). "HPA Pathology Atlas defines MAGEA4 to be “cancer enhanced” in lung cancer in the TCGA, with comparable expression in head and neck cancer." (PMID 37835579, 2023). "Several reports confirmed our findings and showed broad RNA or protein expression of MAGEA4 not only in lung cancer, but also in other cancer types." (PMID 37341056, 2023). "In addition, MAGEA4 was shown to promote apoptotic cell death induced by chemotherapeutic agents in lung cancer cells." (PMID 34788311, 2021).
esophageal cancer (15 papers, 2018 to 2025). A primary or metastatic malignant neoplasm involving the esophagus. "This group of genes has a well-established role in other cancers and MAGEA4 has been previously demonstrated to be overexpressed in esophageal cancer." (PMID 38604503, 2024). "In addition, SPAG1 and MAGEA4 are immunogenic proteins, where peptides derived from MAGEA4 significantly induced tumor-specific cytotoxic T cell response in vitro and in vivo in human esophageal cancer and SPAG1-induced humoral immune responses in certain cancers." (PMID 33287876, 2020). "For esophageal cancer, the GeneCards database ranks CDK4 (cyclin-dependent kinase 4), DNMT3B (DNA methyltransferase 3 beta), and MAGEA4 (MAGE family member A4) as the top three relevant genes." (PMID 33273919, 2020). "Similarly, we also found that knockdown of DUXAP8 could impair esophageal cancer cells proliferation and invasion, and DUXAP8 expression is positively related to oncogenes MAGEA4 and GABRA3 expression, but negatively related to tumor suppressors INPP5A and TIMP4." (PMID 29926523, 2018). "Furthermore, DUXAP8 is positively related to MAGEA4, GABRA3 expression, and negatively related to INPP5A, TIMP4 expression in esophageal cancer; LINC00460 is positively related to ITGA3, LAMC2 expression, and negatively related to FOXO4, KLF15 expression in esophageal cancer." (PMID 29926523, 2018).
breast carcinoma (13 papers, 2007 to 2025). "In BRCA1-mut breast cancer, KANK4, MFGE8, LINC00346, and A100A1 were upregulated (more than 3-fold change), and in BRCA2-mut breast cancers, MAGEA4 was highly expressed (more than 4-fold change)." (PMID 40647506, 2025). "In order to verify the regulation effects of CDKN2A/MAGEA4 in breast cancer progression, in vitro experiments are performed." (PMID 37857018, 2023). "MAGEA4 is also a therapeutic target in breast cancer where we observed hypomethylation in 18% of BRCA cases." (PMID 25631659, 2015). "MAGEA2, MAGEA3, MAGEA4, MAGEA6, and MAGEA12 are up-regulated in the CDKN2A alteration group, amongst which MAGEA3 (HR=1.61[1.27-2.04], p=8.2e-5), MAGEA4 (HR=1.38[1.08-1.77], p=0.011), and MAGEA12 (HR=1.65[1.10-2.48], p=0.015) are accompanied by worse prognosis in breast cancer." (PMID 37857018, 2023). "Of 16 CTAGs examined in the first panel of 42 breast cancer samples, seven antigens were found not to be expressed in any of the specimens: SSX2, SSX4, CTAG2, CAGE1, MAGEA1, MAGEA4 and MAGEA11." (PMID 17650306, 2007).
head and neck cancer (12 papers, 2018 to 2025). A primary or metastatic malignant neoplasm affecting the head and neck. "The MAGEA4, belong to Class I cancer testis antigens, is upregulated in head and neck cancer." (PMID 35378133, 2022). "We also identified that MAGE family member A4 (MAGEA4) was highly expressed in lung and head and neck cancer." (PMID 33287876, 2020).
sarcoma (11 papers, 2013 to 2025). A usually aggressive malignant neoplasm of the soft tissue or bone. "However, it does not seem that everything can go smoothly and the TME of mild progressive STSs and highly aggressive sarcomas like UPS, MFS, and MPNST would have different roles for NY-ESO-1 and MAGEA4 according to another report." (PMID 40149640, 2025).
non-small cell lung carcinoma (9 papers, 2008 to 2025). A group of at least three distinct histological types of lung cancer, including non-small cell squamous cell carcinoma, adenocarcinoma, and large cell carcinoma. "Particularly, MAGEA4 has been associated with poor prognosis in non-small cell lung cancer." (PMID 41345672, 2025).
osteosarcoma (9 papers, 2011 to 2025). A usually aggressive malignant bone-forming mesenchymal neoplasm, predominantly affecting adolescents and young adults. "To test this, we conducted in vitro cytotoxicity assays with HLA-A*02:01 and MAGEA4 (A2M4) TCR-engineered T cells (TCR-T) against the U2-OS osteosarcoma cell line, which naturally expresses HLA-A*02:01 and MAGEA4." (PMID 40246846, 2025). "In the current study, we show that MAGEA4 and MAGEA10 proteins are incorporated into extracellular vesicles released by mouse fibroblast and human osteosarcoma U2OS cells and are expressed, at least partly, on the surface of released EVs." (PMID 31217903, 2019). "Most of the cell lines do not express MAGEA proteins, one of the few exceptions is human osteosarcoma cell line U2OS, which expresses several MAGEA proteins including MAGEA4 and to lesser extent MAGEA10." (PMID 31217903, 2019). "In the current study, we show that MAGEA4 and MAGEA10 proteins are incorporated into naturally occurring EVs released by mouse fibroblast and human osteosarcoma U2OS cells and are expressed on the surface of EVs." (PMID 31217903, 2019).
gastric cancer (8 papers, 2016 to 2025). A primary or metastatic malignant neoplasm involving the stomach.
seminoma (5 papers, 2011 to 2025). A radiosensitive malignant germ cell tumor found in the testis (especially undescended), and extragonadal sites (anterior mediastinum and pineal gland). "According to earlier publications, each histologic subtype has different gene signatures identified by transcriptional profiling: seminomas have overexpressed spermatogenesis-associated genes like PRAME, MAGEA4 and SPAG1 while NSGCTs have overexpressed regulatory genes such as DNMT3B and SOX2." (PMID 40011822, 2025). "Consistently, MAGEA4, a classical seminoma marker, was significantly downregulated in metastatic seminomas compared to non-metastatic cases, with even lower expression observed in embryonal carcinomas." (PMID 41203637, 2025).
testicular cancer (4 papers, 2017 to 2025). A primary or metastatic malignant neoplasm that affects the testis. "Furthermore, a new connection between TWIST1 and the testicular cancer antigen MAGEA4 was recently reported for KYSE30 cells." (PMID 29299035, 2017).
bladder cancer (3 papers, 2024 to 2025). "MAGEA4 expression in these tumors was associated with progression to MIBC (HR = 7.417, p = 0.013) based on univariate analyses, whereas MAGEA9 expression was further predictive of bladder cancer progression." (PMID 38254738, 2024). "It was found that frequencies of genomic alterations among MAGEA family members in bladder cancer were MAGEA1 1.8%, MAGEA2 1.6%, MAGEA3 1.9%, MAGEA4 1.6%, MAGEA6 2.6%, MAGEA8 1.7%, MAGEA10 2%, MAGEA11, 2.1%, and MAGEA12 2.4%." (PMID 38254738, 2024). "A data analysis of bladder cancer patients further uncovers the possibilities of utilizing MAGEA2, MAGEA3, MAGEA4, MAGEA6, MAGEA10, MAGEA11, and MAGEA12 members as diagnostic biomarkers for bladder cancer." (PMID 38254738, 2024). "Interestingly, MAGEA2, MAGEA3, MAGEA4, MAGEA6, MAGEA10, MAGEA11, and MAGEA12 exhibited significant differences in their expression in bladder cancer compared to normal bladder samples." (PMID 38254738, 2024).
adenoma (2 papers, 2016 to 2021). A neoplasm arising from the epithelium. "Among tested single autoantibody markers, anti-MAGEA4 was found to have good diagnostic potential for detecting early stage CRC (sensitivity=11%; 95% CI, 4−28%) and advanced adenomas (sensitivity=12%; 95% CI, 7−20%) in our analysis." (PMID 26909861, 2016). "Anti-MAGEA4 was found to have best diagnostic potential for detecting early stage CRC and advanced adenomas, with sensitivities of 11% (95% CI, 4−28%) and 12% (95% CI, 7−20%), respectively, at a specificity of 96%." (PMID 26909861, 2016). "Using the Sengenics CTA protein array, pooled benign controls (n = 2, adenomas) showed detectable autoantibodies (Z-score > 3) against five antigens (AURKA, CTAG1A, CYP450 3A4, MAGEA4 and RAF1)." (PMID 34681879, 2021). "Among all single markers, anti-MAGEA4 showed the highest sensitivity for detecting early stage CRC (11%, 95% CI, 4−28%) and advanced adenomas (12%, 95% CI, 7−20%) at a specificity of 96% (95% CI, 90−98%)." (PMID 26909861, 2016). "Anti-MAGEA4 exhibited the highest sensitivity for detecting early stage CRC and advanced adenoma." (PMID 26909861, 2016).
carcinosarcoma (1 paper, 2020). A malignant tumor composed of a mixture of carcinomatous and sarcomatous elements. "Previous studies have also linked overexpression of MAGEA4 with the carcinosarcoma subtype and with poor survival in high grade EC." (PMID 32899298, 2020).
chordoma (1 paper, 2022). Chordomas are rare malignant tumors arising from embryonic remnants of the notochord in axial skeleton. "The effects of many immune checkpoints, including LAG3, TIM3, SIRPα, HHLA2, MAGEA4, VISTA and TIGIT, have been validated in chordoma, and five of them (TIM3, SIRPα, HHLA2, MAGEA4 and VISTA) were only evaluated in preclinical study." (PMID 36612259, 2022).
cutaneous squamous cell carcinoma (1 paper, 2023). "(J) Immunohistochemistry staining of MAGEA4 and ITGA6 in human skin of normal, SCCIS, and cutaneous squamous cell carcinoma (cSCC) samples." (PMID 38099574, 2023).
endometrial tumor (1 paper, 2025). "Based on expression analysis in patient-derived endometrial tumor tissues, we identify two potential targets – fibroblast activation protein (FAP) and melanoma-associated antigen A4 (MAGEA4) – for immunotherapy using an ex vivo vaccine setting." (PMID 41345672, 2025).
glioma (1 paper, 2015). A benign or malignant brain and spinal cord tumor that arises from glial cells (astrocytes, oligodendrocytes, ependymal cells). "Many of these up-regulated TAPPs are common in gliomas and other brain cancers, such as Aim2, EZH2, GP100, Mage-1, MageA4, MageA10, Sart-1, -3, Trp-1, and Sox2." (PMID 26175925, 2015).
lymph node metastasis (1 paper, 2024). "The expression of MAGEA3 (P = 0.0021) and MAGEA4 (P < 0.0001) in serum exosomes were high expression and MAGEA3 level was positively correlated with lymph node metastasis of LUAD patients." (PMID 38555374, 2024).
peritoneal disease (1 paper, 2020). "The shape of peritoneal disease was associated with the abundance of MAGEA4 (= 0.04, τ = − 0.343)." (PMID 32253542, 2020).
sickle cell disease (1 paper, 2020). Sickle cell anemias are chronic hemolytic diseases that may induce three types of acute accidents: severe anemia, severe bacterial infections, and ischemic vasoocclusive accidents (VOA) caused by sickle-shaped red blood cells obstructing small blood vessels and capillaries. "Although spermatogonia expressing MAGEA4 were observed in treated sickle cell disease patients within our cohort with a density comparable to the NT reference group, a reduction of the 5mC spermatogonial subpopulation suggests a possible developmental arrest." (PMID 31947706, 2020).
teratocarcinoma (1 paper, 2011). A germ cell tumor characterized by the presence of an embryonal carcinoma component and a teratoma component. "Moreover, we detected different expression pattern of MAGE-A4/Magea4 in both human and mouse pluripotent and teratocarcinoma cells." (PMID 21785609, 2011).